PLD3 (phospholipase D family member 3)
Description:
Lysosomal 5'->3' exonuclease that functions in nucleic-acid sensing by immune cells. Hydrolyzes phosphodiester bond in single-stranded RNA and DNA molecules, with a higher efficiency for molecules with 5' uridine and guanosine residues. It can stall at certain sites and does not necessarily proceed to complete exonucleolytic degradation, thereby producing nucleoside 3'-monophosphates but also 5'-end 5'-hydroxy deoxyribonucleotide/ribonucleotide fragments. Through the processing of self and exogenous RNA and DNA molecules, provides molecular signals to toll-like receptors (TLRs) in innate immunity. Partially redundant with PLD4, it cooperates with the RNase T2/RNASET2 to generate 2',3'-cGMP and cytidine-rich RNA fragments that occupy the two TLR7 ligand-binding pockets, to trigger receptor activation and signaling. Degrades mitochondrial CpG-rich ssDNA fragments to prevent TLR9 activation and autoinflammatory response, but it can cleave viral RNA to generate ligands for TLR7 activation and initiate antiviral immune responses. Can exert polynucleotide phosphatase activity toward 5'-phosphorylated single-stranded DNA substrates although at a slow rate. Regulates the homeostasis and interorganellar communication of the endolysosomal system with an overall impact on cellular removal of dysfunctional organelles via autophagy as well as proper protein and lipid turnover. May play a role in myotube formation in response to ER stress. Can alternatively catalyze the transfer (transphosphatidylation) of a glycerol group between (S,R)- lysophosphatidylglycerol (LPG) and monoacylglycerol (MAG). The reaction is characterized by an R-to-S stereo-inversion which is essential for the resistance of the produced (S,S)-bis(monoacylglycero)phosphates (BMPs) to lysosomal degradation. The resulting BMPs, are phospholipids required for the formation of lysosomal intralumenal vesicles (ILVs) where lipid degradation can occur.
Synonyms: HU-K4; AD19; HUK4; SCA46
Tractability: Small molecule: a structure with a bound ligand is known; a high-quality ligand is known. Antibody: UniProt places it where antibodies can reach, with high confidence; UniProt predicts a signal peptide or a membrane-spanning region. PROTAC: UniProt records ubiquitination sites on it; ubiquitination databases record sites on it; its protein half-life has been measured; a small molecule that binds it is known.
Target class: Enzyme; Phosphodiesterase
Gene: Protein-coding gene on chromosome 19 (40,348,453 to 40,389,472, forward strand). Ensembl gene ENSG00000105223.
Subcellular location: Lysosome lumen; Early endosome membrane; Late endosome membrane; Endosome membrane; Endoplasmic reticulum membrane; Golgi apparatus membrane
Subcellular location (Human Protein Atlas): Cytosol; Endoplasmic reticulum; Nucleoplasm
Pathways (Reactome):
Immune System: Role of phospholipids in phagocytosis
Metabolism: Synthesis of PG
Gene Ontology:
Molecular function: 5'-3' DNA exonuclease activity; 5'-3' RNA exonuclease activity; acyltransferase activity, transferring groups other than amino-acyl groups; protein binding; catalytic activity
Biological process: innate immune response; negative regulation of toll-like receptor 9 signaling pathway; positive regulation of intralumenal vesicle formation
Cellular component: early endosome membrane; endoplasmic reticulum; endoplasmic reticulum membrane; endosome membrane; extracellular exosome; Golgi membrane; late endosome membrane; lysosomal lumen; lysosome; endomembrane system; cytoplasm
Genetic constraint (gnomAD): Loss-of-function variants: 31 observed, 57.52 expected, observed/expected ratio (o/e) 0.54, 90% interval 0.4 to 0.73. The upper end of that interval is the gene's LOEUF score, 0.73, which puts it in group 2 of 6, group 1 being the genes least tolerant of losing a copy. Missense variants: 595 observed, 654.45 expected, observed/expected ratio (o/e) 0.91, 90% interval 0.85 to 0.97. Synonymous variants: 264 observed, 271.75 expected, observed/expected ratio (o/e) 0.97, 90% interval 0.88 to 1.08.
Homologues: Orthologues: chimpanzee PLD3 (99% identical), macaque PLD3 (99% identical), dog PLD3 (97% identical), pig PLD3 (96% identical), guinea pig PLD3 (94% identical), mouse Pld3 (93% identical), rabbit PLD3 (93% identical), rat Pld3 (88% identical), tropical clawed frog pld3 (52% identical), zebrafish pld3 (51% identical), Drosophila melanogaster Pld3 (42% identical), Drosophila melanogaster CG43345 (37% identical), and 4 more. Paralogues in human: PLD4 (42% identical), PLD5 (33% identical).
Diseases named in the same sentence as PLD3 in open-access papers:
PLD3 is named in the same sentence as 68 diseases in open-access papers, as found by Europe PMC text mining. Sharing a sentence is not in itself a finding about the gene and the disease. The quoted sentences say what the papers report.
Alzheimer disease (29 papers, 2014 to 2025). A progressive, neurodegenerative disease characterized by loss of function and death of nerve cells in several areas of the brain leading to loss of cognitive function such as memory and language. "Genetic variants in PLD3 have previously been shown to double the risk of developing Alzheimer's disease." (PMID 37994783, 2024). "Recent studies suggest that Alzheimer’s disease-associated mutations in PLD3 abrogate its putative phospholipase activity and modulating PLD3 levels has been shown to cause an enlargement of endolysosomal vesicles." (PMID 39231962, 2024). "Mutations of PLD3 are considered to be a genetic factor involved in late onset Alzheimer’s disease associated with an increased processing of APP to Aβ." (PMID 34440765, 2021). "Overexpression of PLD3 leads to a significant reduction of intracellular amyloid β precursors, which can reduce the risk of Alzheimer's disease." (PMID 32602849, 2020). "Next-generation sequencing studies have reported that rare variants in PLD3 were associated with increased risk of late-onset Alzheimer’s disease (LOAD) in European cohorts." (PMID 30837833, 2019). "Whole-exome sequencing has revealed a rare missense variant in PLD3 gene (rs145999145) to be associated with late onset Alzheimer’s disease (AD)." (PMID 30208929, 2018). "Recently, a whole-exome sequencing (WES) study showed that a rare variant rs145999145 composed of p.Val232Met located in exon 7 of the phospholipase D3 (PLD3) gene confers a doubled risk for late-onset Alzheimer’s disease (AD)." (PMID 25478031, 2014). "While further work is needed to clarify the potential role of PLD3 as an Alzheimer's disease risk gene or disease modulator, additional work is also required to clarify the pathway(s) where it might modulate disease." (PMID 37994783, 2024). "Phospholipase D3 (PLD3) polymorphisms are linked to late-onset Alzheimer’s disease (LOAD)." (PMID 37225734, 2023). "We followed the expression, proteolytic processing, and intracellular distribution of genetic PLD3 variants previously associated with Alzheimer’s disease and investigated each variant's effect on the 5′ nuclease activity of PLD3, finding that some variants lead to reduced activity, but others not." (PMID 33288674, 2021). "A rare variant in phosphlipase D3 (PLD3) was linked to Alzheimer’s disease (AD) risk, but both the impact of the variant on protein’s function and the role of PLD3 in sporadic AD are unknown." (PMID 33830999, 2021). "Besides its role in the innate immune system, PLD3 previously received considerable attention, as genetic variants in PLD3 were shown to increase the risk of developing Alzheimer’s disease (AD)." (PMID 33288674, 2021). "Interestingly, mutations in PLD3 have been linked to Alzheimer’s disease although this has become somewhat controversial with subsequent studies refuting the initial report." (PMID 29368044, 2018). "These include genes such as NUSAP1 and MS4A6A that are associated to glomerulonephritis, an IgA nephropathy; GPBAR1 that is highly expressed in intestinal monocytes of patients with inflamed Crohn's disease, and; SYNJ1 and PLD3 that are both associated to Parkinson's disease and Alzheimer's disease." (PMID 26338775, 2015). "In addition, it would be interesting in future studies to test whether the Alzheimer’s disease-associated mutations in PLD3 that disrupt its putative phospholipase activity result in a defect in autophagosome degradation." (PMID 39231962, 2024). "This suggests that PLD3's association to neurodegenerative diseases might be related to neuroinflammatory component of these diseases, similarly as has been shown for many Alzheimer's disease-associated genetic variants that are enriched in enhancer regions active in inflammatory cells." (PMID 26338775, 2015). "Human 5′–3′ exonuclease PLD3, a member of the phospholipase D family of enzymes, has been validated as a therapeutic target for treating Alzheimer's disease." (PMID 39325669, 2024).
Alzheimer disease (continued). "There have been few studies on PLD3 function, most of which have focused on Alzheimer’s disease, actin generation in myocytes, and the regenerative potential of hematopoietic stem cells." (PMID 37978168, 2023). "Phospholipase D3 (PLD3) and phospholipase D4 (PLD4), the most recently described lysosomal nucleases, are associated with Alzheimer’s disease, spinocerebellar ataxia, and systemic lupus erythematosus." (PMID 33288674, 2021). "Clinically, PLD3 is closely related to Alzheimer’s disease, and it has been demonstrated to be involved in amyloid precursor protein processing in Alzheimer’s disease pathogenesis." (PMID 34447787, 2021). "In this review we discuss our current knowledge of the risk genes APOE4, BIN1, CD2AP, PICALM, PLD3 and TREM2 and their impact on endolysosomal (dys)regulations in the light of late-onset Alzheimer’s disease pathology." (PMID 31159836, 2019). "For example, we found Alzheimer’s Disease risk genes APOE, PLD3, TREM2, UNC5C, AKAP9, and ADAM10 in our orthologous gene list." (PMID 30382841, 2018). "PLD3 may be involved in the pathogenesis of Alzheimer’s disease through the processing of amyloid-precursor protein." (PMID 40709343, 2025). "Importantly, we detected 25 HLA epitopes derived from 15 genes associated with Alzheimer’s and related dementias such as Tau, PLD3 (Alzheimer’s disease), TDP-43, FUS (Frontotemporal dementia), and PARK7, VPS35 (Lewy Body dementia)." (PMID 40568088, 2025). "Whole exome sequencing (WES) of 14 late-onset Alzheimer’s disease (LOAD) families and confirmation analysis of several large LOAD cases revealed Val232Met variation in PLD3, implying that rare coding variants of PLD3 might increase the risk of LOAD12." (PMID 34815492, 2021). "However, another recent and critical study that examined the role of PLD3 in the development of Alzheimer's disease pathology reaffirmed the axonal origins of the lysosome buildup at neuritic plaques and linked their accumulation/enlargement to axonal conduction blockades." (PMID 39632089, 2024). "Variants in phospholipase D3 (PLD3) may increase the risk of Alzheimer's disease and spinocerebellar ataxia, but this hypothesis has not been fully confirmed." (PMID 34267643, 2021). "PLD3 research is currently focused on the regenerative potential of hematopoietic stem cells, actin production in myocytes, and Alzheimer’s disease, with no reports of tumor-related studies." (PMID 37978168, 2023). "Indeed, the PLD3 - Phospholipase D3 is an important key in lipids metabolism and may be involved in the Amyloid Precursor Protein (APP), already been related to Alzheimer ́s Disease (AD)." (PMID 36046788, 2022).
neuroblastoma (6 papers, 2014 to 2024). Neuroblastoma (NB) is the most common solid, extracranial childhood tumor. "Herein we identify PLD3 as a key lysosomal 5’−3’ exonuclease with a major activity towards mtDNA, as evidenced by the enrichment of mitochondrial genes in lysosomes isolated from PLD3−/− and PLD3 SNP variant rescued neuroblastoma cells." (PMID 37225734, 2023). "Similar results were observed upon PLD3 depletion in SH-SY5Y human neuroblastoma cells." (PMID 39231962, 2024). "Consequently, we isolated lysosomes from PLD3-transfected NSC34 cells (a murine neuroblastoma line) to assess PLD activity, we found that PLD3 containing lysosomes had significantly increased phospholipase D activity compared to non-transfected lysosomes." (PMID 33830999, 2021). "Given PLD3 is highly enriched in neuronal lysosomes and given its connection to LOAD33,34, we opted to study its role in SH-SY5Y neuroblastoma cells." (PMID 37225734, 2023). "A similar degree of colocalisation was observed for PLD3–GFP and APP in neuroblastoma SH-SY5Y cells and PLD3–GFP was detected in endosomes positive for the retromer protein VPS35." (PMID 29368044, 2018). "The human cerebrum, astrocytes, neuronal progenitor cells, NTera2 teratocarcinoma-derived neurons, SK-N-SH neuroblastoma, IMR-32 neuroblastoma, U-373MG glioblastoma, T98 glioblastoma, and HMO6 immortalized microglia constitutively expressed PLD1, PLD2, and PLD3 transcripts (lanes 1, 3 to 10)." (PMID 25478031, 2014).
spinocerebellar ataxia (6 papers, 2019 to 2022). "A mutation in PLD3 has recently been linked to an autosomal dominant form of spinocerebellar ataxia, even though it remains questionable if the mutation in PLD3 is causative for the disease." (PMID 33288674, 2021). "In addition, a pathogenic variant in PLD3 that reduces PLD3 activity has been reported in a family with spinocerebellar ataxia." (PMID 31231646, 2019). "RT-qPCR revealed that the mRNA transcription levels of four ataxia-related genes (ataxin 10 (Atxn10), protein phosphatase 2 regulatory subunit B beta (Ppp2r2b), protein kinase C gamma (Prkcg), and phospholipase D3 (Pld3)) were significantly changed in the Zfp212-KO Cb compared to those in the WT." (PMID 34815492, 2021). "As in the case of AD, this genetic association was also challenged because Pld3 knockout mice do not develop any signs of spinocerebellar ataxia." (PMID 33288674, 2021). "Notably, significant downregulation of Zfp212 and PLD3 was observed in the Cb of alcohol-induced ataxia mice, suggesting that ZNF212 is an essential protein that maintains Purkinje cell health and regulates the level of PLD3 in the Cb." (PMID 34815492, 2021).
Parkinson disease (5 papers, 2014 to 2019). A progressive degenerative disorder of the central nervous system characterized by loss of dopamine producing neurons in the substantia nigra and the presence of Lewy bodies in the substantia nigra and locus coeruleus. "Next, we studied PLD3 mRNA and protein expression in frozen tissues of the frontal cortex, derived from four patients that died from non-neurological causes, six amyotrophic lateral sclerosis patients, four Parkinson’s disease patients, and seven AD cases." (PMID 25478031, 2014). "By quantitative RT-PCR (qPCR), western blot, immunohistochemistry, and bioinformatics analysis, we studied PLD3 expression patterns and levels in a series of AD and control brains, including amyotrophic lateral sclerosis, Parkinson’s disease, multiple system atrophy, and non-neurological cases." (PMID 25478031, 2014).
amyloidosis (3 papers, 2018 to 2023). A disorder characterized by the localized or diffuse accumulation of amyloid protein in various anatomic sites. "Together with our data, this suggests that PLD3 has complex effects on endolysosomes that are age- and context-dependent and that axons are particularly susceptible to endolysosomal abnormalities, especially in the presence of amyloidosis." (PMID 36450991, 2022). "Using disease and functional analyses, we have identified changes in a number of biomarkers involved in amyloidosis and AD including PLD3." (PMID 37762058, 2023). "Accordingly, we have found an inverse correlation between PLD3 mRNA expression levels and the burden of hippocampal β-amyloid assessed by two measurements, averaged deposit of β-amyloid and amyloid plaque score (APS)." (PMID 30208929, 2018). "Furthermore, our data with PLD3 overexpression in WT mice also led to occasional formation of small axonal swellings with ELPVs, suggesting that excessive PLD3 by itself can have detrimental effects, independent of amyloidosis." (PMID 36450991, 2022).
autoimmune disease (2 papers, 2021). A disorder resulting from loss of function or tissue destruction of an organ or multiple organs, arising from humoral or cellular immune responses of the individual to their own tissue constituents. "A recent report argued that both PLD3 and PLD4 have 5’ exonuclease activity and implicated this activity in the function of antigen presenting cells in the context of autoimmune diseases." (PMID 33830999, 2021). "PLD4 variants have been linked to autoimmune disease, particularly rheumatoid arthritis, but there is no such association with PLD3." (PMID 33830999, 2021).